BCL2 (BCL2 apoptosis regulator)
Diseases named in the same sentence as BCL2 in open-access papers (continued):
Sharing a sentence is not in itself a finding about the gene and the disease.
breast carcinoma (continued). "The exact mechanism of differential BCL2 protein expression in breast cancer is complex." (PMID 20664598, 2010). "Thus, we evaluated the effects of ABL-N on the expression of anti-apoptotic protein Bcl-2 and the pro-apoptotic proteins Bax and Bad in breast cancer cells." (PMID 20096139, 2010). "We determined whether BCL-W and BCL2 regulate ICI response in human breast cancer cells, and whether any effects involve changes in apoptosis and/or BECN1-associated autophagy." (PMID 20062536, 2010). "The expression of BCL-2 most confined to the ER-positive breast cancer cells, ER-positive was a necessary condition in endocrine therapy; the patient with BCL-2 high expression having a good prognosis, maybe more sensitivity to endocrine therapy." (PMID 20691103, 2010). "Moreover, CTL clones recognizing Bcl-2-derived epitopes efficiently killed cancer cells of different origin, e.g., colorectal cancer, breast cancer and melanoma cells." (PMID 21304176, 2010). "This inhibition may contribute to the down-regulation of the levels of Bcl-2 protein and up-regulation of the levels of Bax protein in the human breast cancer cells." (PMID 19796390, 2009). "In MCF-7 human breast cancer cells, caspase 8 activation appears to be due to the activation of caspase 9 within the apoptosome, as caspase 8 processing is inhibited by overexpression of the anti-apoptotic protein Bcl2." (PMID 19609365, 2009). "In addition, the taxanes inactivate the Bcl-2 protein and induce apoptosis in breast cancer cells in vitro." (PMID 21556249, 2009). "Our findings have showed that BER suppresses the growth, migration and invasion in highly-metastatic human breast cancer cells by possibly inhibiting Akt and NF-κB signaling with their upstream target c-Met and downstream targets Bcl-2/Bax, osteopontin, VEGF, MMP-9 and MMP-2." (PMID 19796390, 2009). "For instance, in breast cancer cells, activated Raf conferred resistance to the chemotherapeutic drugs doxorubicin and paclitaxel by inducing the expression of the drug pump Mdr-1 and the Bcl-2 antiapoptotic protein." (PMID 19698189, 2009). "A number of studies, covering about 5000 patients, with breast cancer at different stages showed that Bcl-2 over-expression correlated to a differentiated phenotype and a favorable prognosis in patients subjected to local-regional, hormonal or cytotoxic therapies." (PMID 19331661, 2009). "We showed previously that the prognostic effect of BCL2 status is maximal in the first five years after a diagnosis of breast cancer and wanes thereafter, suggesting that its utility as a diagnostic adjunct may be limited to this period." (PMID 18510726, 2008). "In summary, we have shown that BCL2 is an independent prognostic marker in two large series of breast cancer and, here, provide an estimate of the average size of this association with outcome in a meta-analysis on 16 other series totalling over 5,000 patients." (PMID 18510726, 2008). "Options for refinement of our approach might include incorporation of other biomarkers that have been shown to predict prognosis independently of conventional prognostic factors for breast cancer, for example Bcl-2." (PMID 18194560, 2008). "Bcl-2 overexpression is described in approximately 80% of primary breast cancer but a clear association with a chemoresistance has not been shown to date." (PMID 18380893, 2008).
breast carcinoma (continued). "Furthermore, it remains to be established if other proteins e.g. Wnt11 or bcl homologues potentiate the tumour suppressor role of BCL2 in breast cancer." (PMID 18510726, 2008). "Results of meta-analysis of expression of Bcl-2 and outcome in Breast Cancer." (PMID 18510726, 2008). "In the present work we assessed expression of Bcl-2 and Bag-1 in primary breast cancer specimens." (PMID 18430249, 2008). "Bcl-2 is positively regulated by hormonal receptor pathways in breast cancer." (PMID 17430582, 2007). "The presence of bcl-2 in breast cancers positively correlates with ER." (PMID 17285125, 2007). "The combined dataset profile included two known molecular markers of breast cancer: BCL2 and ESR1." (PMID 17883867, 2007). "Similarly, celecoxib also reduced both COX-2 and Bcl-2 expression in an MTag mouse model of breast cancer." (PMID 17612393, 2007). "Targeted therapy against Bcl-2 protein with the use of AS ODNs might enhance the effects of chemotherapy in patients with breast cancer." (PMID 16280040, 2005). "Because the enforced overexpression of Bcl-2 can act as an antioxidant in response to DNA damage, the decreased chemosensitivity of the Bcl-2-transfected breast cancer cells to DNA-damaging agents, including DOX and MMC, may be explained by this effect." (PMID 16280040, 2005). "One determining factor might be the differential expression of Bcl-2 and Bcl-xL in breast cancer cells." (PMID 16280040, 2005). "In fact, overexpression of Bcl-2 and Bcl-xL is observed in several cancers, including hematologic malignancies, as well as a range of solid tumors, including nasopharyngeal, colorectal, prostate, and breast cancer." (PMID 16280040, 2005). "Furthermore, we studied the effect of Bcl-2 gene transfection on the chemosensitivity of a breast cancer cell line that normally expresses a low basal level of Bcl-2." (PMID 16280040, 2005). "This kind of observation is not unique, however, since expression of Bcl-2 is also associated with good prognosis in breast cancer, for example." (PMID 12373595, 2002). "Thus, Bcl-2 protein, thought to be antiapoptotic, exhibits parodoxical expression in human breast carcinomas." (PMID 9252201, 1997). "Furthermore, both 8b and 10 decreased in Bcl2 levels in breast cancer cells." (PMID 42152001, 2026). "In breast cancer (BC) cells, the evasion of apoptosis is often facilitated by the upregulation of Bcl-2 expression, frequently driven by estrogen stimulation." (PMID 40841912, 2025). "Interestingly, Bcl-2 has been reported to localize to the nucleus in various cancer types including breast cancer, endometrial carcinoma, squamous cell carcinoma, and astrocytoma, where it appears to take part in a multiprotein complex comprising CDK1, PP1, and nucleolin." (PMID 38228372, 2024). "Similarly, GATA3 expression was positively correlated with BCL2 expression in breast cancer." (PMID 38668712, 2024).
breast carcinoma (continued). "Their mode of action involves the direct or indirect regulation of anti-apoptotic (such as Bcl-2 and Bcl-x) and pro-apoptotic (such as Bcl-10 and Bax) proteins, leading to the expression of caspase-9, caspase-3, and caspase-7, key players in apoptosis to induce the apoptosis of breast cancer cells." (PMID 38585632, 2024). "Recently, EVs derived from cancer cells were shown to reduce the apoptosis rate via upregulation of BCL2 in other cancer cells, and tumor-derived EVs containing extracellular matrix molecules induced mutations in PIK3CA, which promoted proliferation and invasion in breast cancer." (PMID 39474419, 2024). "Therefore, we concluded that an increase in growth factors, e.g., Vascular Endothelial Growth Factor (VEGF), Tumour Growth Factor-beta (TGF-β) and B-cell lymphoma (Bcl2), under the influence of these variables plays a crucial role in the metastasis of breast cancer." (PMID 38956273, 2024). "Also, breast cancer cells are resistant to clinical trial drugs such as the Bcl-2/Bcl-xL inhibitor, ABT-263, which may result from increased Mcl-1 expression." (PMID 37537243, 2023). "In addition, it is well known that estrogen receptor (ER)-negative breast cancer is more sensitive to taxanes than ER-positive breast cancer, and one possible reason is that ER regulates Bcl-2-induced taxane resistance in breast cancer cells by inhibiting apoptotic cell death." (PMID 37569629, 2023). "Therefore, targeting Bcl-2 may provide a potential therapeutic strategy for angiogenesis, and investigation of more effective Bcl-2-based anti-angiogenic agents may offer potential novel breast cancer therapy." (PMID 37237269, 2023). "However, pharmacological inhibition of Bcl-2 and Bcl-xL, alone or combination, in breast cancer cells causes the induction of Mcl1 and therefore fails to inhibit tumor cell growth." (PMID 36853387, 2023). "Therefore, simultaneous inhibition of MCL-1 and BCL-2 may further inhibit the growth of ER+ breast cancer cells and reverse cell resistance to venetoclax." (PMID 37352173, 2023). "However, the possibility that those high Bcl-2 tumors were less prevalent in nH Black patients’ cases might provide insight into our understanding of the racial/ethnic disparity in breast cancer incidence and outcomes." (PMID 37370761, 2023). "Interestingly, luteolin triggered apoptosis through the downregulation of the human telomerase reverse transcriptase (hTERT) via the NF-κB/c-Myc pathway, which correlated to increased Bax/Bcl-2 ratio and caspase-3 protein expression in human breast cancer cells." (PMID 37240168, 2023). "Furthermore, multiple Bcl-2 inhibitors are being tested in clinical studies against various cancer types, and activity has been widely reported in pre-clinical models such as human breast cancer cells MCF-7 and MDA-MB-231 and human lung cancer cell A549." (PMID 37834104, 2023). "SGK1 and Bcl-2 may play biological roles in breast cancer development and/or progression." (PMID 37370761, 2023). "Targeted therapy against BCL-2 may improve the effects of chemotherapy in breast cancer patients." (PMID 37193964, 2023). "A recent study showed that FASN inhibition increases mitochondrial priming and enhances breast cancer cell sensitivity to BCL2-targeting BH3 mimetics which may directly activate the apoptotic machinery and generate more potent and longer-lasting antitumor responses in a clinical setting." (PMID 38049490, 2023). "Therefore, prognostic role of Bcl2 expression in breast cancer is subtype-specific, and Bcl2 expression differs according to the molecular subtype and is a good prognostic marker for only luminal A breast cancer." (PMID 37273492, 2023). "For example, NK-Exos loaded with small interfering RNA from BCL-2 enhanced intrinsic apoptosis in breast cancer (BC) cells." (PMID 36797782, 2023).
breast carcinoma (continued). "The Bcl-2 proteins are less expressed in triple-negative breast cancer cells compared to other BC cells, therefore, being less sensitive to ABT–199 (a BH3 mimetic drug)-induced cell death." (PMID 37627592, 2023). "Thus Bcl-2 expression could be indicative of increased estrogen signaling in luminal breast cancers, which upon anti-estrogen treatment would be reduced along with cancer cell proliferation." (PMID 35053443, 2022). "Disrupting such IP3R/Bcl-xL complexes could therefore result in Ca2+-driven cell death, as observed in several Bcl-2-dependent cancer in which Bcl-2 was displaced from IP3Rs or antagonize breast cancer cell migration, a process controlled by Bcl-xL at the level of the IP3R." (PMID 34750538, 2022). "However, in breast cancer, Bcl-2 expression has been described as a promising prognostic factor." (PMID 36299777, 2022). "Moreover, simultaneous exposure of naringenin (100 μM) and BPA (10 μM) in breast cancer cells has shown an apoptotic effect due to a decrease in anti-apoptotic Bcl-2 proteins, mechanisms that may also play a role in the present study." (PMID 36235125, 2022). "The difference in the incidence of AA genotype between the two populations could be the reason for the absence of a relationship between breast cancer and BCL2 C(-938) A gene polymorphism in our study (7.5% vs 31%)." (PMID 35320970, 2022). "Moreover, a patent of a luteolin pharmaceutical composition from the USA has treated and prevented the cancerous cells of liver, brain, pancreas, lung, breast cancer, and leukemia via targeting the BCL-2, bromodomains, sirtuins, kinases, and matrix metalloproteinases." (PMID 35458669, 2022). "In addition, the anti-apoptotic protein (BCL2) is a downstream target of GPER in breast cancer and diabetic conditions and thus, could be a therapeutic target for both conditions." (PMID 36558071, 2022). "It has been shown that IFI6 plays anti-apoptosis roles in gastric and breast cancer cells, human myeloma cells and vascular endothelia cells, mainly through stabilizing mitochondrial membrane potential, inhibiting activation of caspase 3 and caspase 9, and decreasing Bax/Bcl-2." (PMID 34399768, 2021). "JC-1 staining assay further suggested that ursolic acid (1~30 μM) could induce mitochondrial depolarization and apoptosis of breast cancer cells, which was achieved by attenuating the anti-apoptotic protein Bcl2 whereas elevating the pro-apoptotic proteins Bax and cleaved PARP." (PMID 34568078, 2021). "The prognostic influence of BCL2 expression might be different across breast cancer subtypes." (PMID 34099764, 2021). "Conversely, in the instance of the Bcl-2 and Bcl-xL anti-apoptotic proteins, their genetically deregulated-over-expression can give rise to similar malignancies, such as B-cell lymphoma, prostate cancer, non-small cell lung cancer, Acute lymphoblastic leukaemia and breast cancer." (PMID 34753495, 2021). "Therefore, increased Bcl-2 expression in MCF-7 cells but reduced Bcl-2 expression in MDA-MB-231 cells by heteronemin may reflect different mechanisms in different types of breast cancer cells." (PMID 34381775, 2021). "Interestingly, in this study, we found that triclabendazole significantly induces apoptosis in breast cancer cells typically swollen with evident large bubbles, including positive for annexin V staining, irregulation of Bax and Bcl-2, activation of caspase-3/7/8/9, and cleavage of PARP." (PMID 34305590, 2021). "Thus, BCL2 might be the most potential downstream target of MUC14-miR-137/miR-429 axis in breast cancer." (PMID 34828282, 2021). "Additionally, BCL2 positivity could be closely related to markers that denote better differentiation of breast cancer cells." (PMID 34099764, 2021).
breast carcinoma (continued). "Although it is still unclear whether high or low levels of anti-apoptotic Bcl-2 proteins in CTCs is correlated with breast cancer metastasis in humans, mice intravenously injected with MDA-MB-435 breast cancer cells overexpressing Bcl-xL increased formation of secondary tumors." (PMID 32708855, 2020). "Similarly, in our recent chemopreventive studies using rat models, we described significant correlation between increase in Bax/Bcl-2 ratio and an increase in caspase-3 expression in mammary carcinoma cells induced by dark fruit peel, oregano, clove buds, and cinnamon." (PMID 33375383, 2020). "Luciferase reporter assay results showed that the increased expression of miR-185-5p in BT-474 cells inhibited the luciferase activity of reporter plasmid with 3′UTR of BCL2, confirming that the miR-185-5p could negatively regulate the BCL2 expression in breast cancer cells." (PMID 32366289, 2020). "Since prodigiosin and PU-H71 were reported to downregulate the level of BCL2 gene transcription in breast cancer cells, and since TNBC is refractory to current treatment, to this end, we determined whether PU-H71, prodigiosin and their combination could inhibit BCL2 in MDA-MB-231 cell line." (PMID 32895397, 2020). "Consequently, it is not unexpected that the amplification and overexpression of pro-survival Bcl-2 proteins, such as Bcl-2 and Mcl-1, are found in many cancer types (e.g., non-small-cell lung cancer, breast cancer, ovarian cancer, prostate cancer, and pancreatic cancer)." (PMID 32260280, 2020). "MCF7 cells depleted of PRMT1 or BRCA1 showed a significant decrease in Bcl-2 protein, but experiments in the presence of MG132, a proteasome inhibitor, and analysis of Bcl-2-mRNA indicated that BRCA1 and PRMT1 might differentially regulate Bcl-2 protein levels in breast cancer cells." (PMID 32764667, 2020). "Meanwhile, another study focused on luminal breast cancer have revealed that GATA3 is frequently mutated and its levels are significantly elevated, and could mediate the transformation of normal cells into breast cancer through deregulation of BCL2, DACH1 and THSD4." (PMID 32538432, 2020). "Indeed, BCL2 is upregulated by estrogens in breast cancer cells, explaining why Bcl2-positive expression in breast cancer may be considered a sign of ER functional activity." (PMID 30630524, 2019). "However, IL-6-mediated STAT3 activation has frequently been suggested to be a protective mechanism in chemotherapy-induced cell death through the increased expression of anti-apoptotic proteins such as Bcl-2 or survivin in solid tumors such as breast cancer and prostate cancer." (PMID 30927911, 2019). "However, one study drew the opposite conclusion that ERβ may reduce Bcl-2 expression in hormone-resistant breast cancer cells." (PMID 31076571, 2019). "Therefore, β2M may promote the survival of tumor cells through the mTORC1/SGK1/Bcl-2 signaling pathway in ER+ breast cancer cells with HER2− (MCF-7 and T47D)." (PMID 30866857, 2019). "BTG1 expression was down-regulated in breast cancer cells and significantly correlated with proliferation, poor overall survival, histological grade, clinic stage, and lymph node metastasis by regulating protein expression levels of Cyclin-D1, Bcl-2, and MMP-9." (PMID 29416786, 2018). "The possible TAMs-modulated drug resistance mechanism involved may be associated with elevation of bcl-2 gene expression and up-regulation of STAT3 signaling in tumor cells, forming IL-10/STAT3/bcl-2 signaling axis accounting for chemoresistance of breast cancer." (PMID 30175384, 2018). "Moreover, it agreed with previous study that inhibition of Hh pathway by itraconazole could induce apoptosis, reduce Bcl2 protein expression and autophagic cell death in breast cancer cells." (PMID 29734730, 2018).